IRS1 (insulin receptor substrate 1)
Diseases named in the same sentence as IRS1 in open-access papers (continued):
Sharing a sentence is not in itself a finding about the gene and the disease.
thyroid cancer (6 papers, 2018 to 2023). "For instance, H19 reduces the cell viability, mobility, and invasion abilities of thyroid cancer cell through downregulating insulin receptor substrate 1 (IRS-1)." (PMID 32425696, 2020). "Remarkably, Wang discovered that lncRNA-H19 inhibited thyroid cancer cell activity, migration and invasion by down-regulating insulin receptor substrate 1 in SW579 and TPC-1 cells." (PMID 30778327, 2019). "Furthermore, H19 has been shown to inhibit Insulin receptor Substrate 1(IRS-1), leading to reduction of cell viability, migration, and invasion in thyroid cancer cells." (PMID 29561759, 2018).
hepatitis C (5 papers, 2011 to 2024). "Proinflammatory cytokine, hepatitis C virus infection or retinoic acid treatment was all reported to decrease IRS-1 protein level, resulting in suppression of insulin signal activity." (PMID 21991327, 2011). "An imbalance in the levels of activating tyrosine-phosphorylated IRS-1, the inhibitory serine-phosphorylated IRS-1, and threonine-phosphorylated Akt seems to play an integral part in the development of IR in hepatitis C." (PMID 26441826, 2015).
ischemia (5 papers, 2018 to 2025). A hypoperfusion of the BLOOD through an organ or tissue caused by a PATHOLOGIC CONSTRICTION or obstruction of its BLOOD VESSELS, or an absence of BLOOD CIRCULATION. "Noting the protective role of cardiac IRS1, the feasibility of ameliorating cardiac insulin sensitivity and heart injury via maintaining IRS1 following ischemia has been underscored." (PMID 32223896, 2020). "In this study, we examined the histological presence of insulin-like growth factor-I (IGF-1) and insulin receptor substrate (IRS-1) in anatomically distinct brain circuits compared with morphological brain damage in a co-morbid rat model of striatal ischemia (ET1) and Aβ toxicity." (PMID 29572520, 2018). "Here we showed that Aβ toxicity and ischemia provoked substantial region-specific increases in the abundance of cells staining for IGF-1 and IRS-1 that encompassed the majority of the ipsilateral hemisphere." (PMID 29572520, 2018).
laryngeal squamous cell carcinoma (5 papers, 2020 to 2023). A squamous cell carcinoma that arises from the larynx. "The authors wish to retract their research article entitled 'lncRNA XIST promotes the progression of laryngeal squamous cell carcinoma by sponging miR‐144 to regulate IRS1 expression', published in Oncology Reports 43: 525‐535, 2020." (PMID 34676882, 2021). "Previous studies have shown that lncRNA XIST promotes the development of laryngeal squamous cell carcinoma (LSCC) through stimulating miR-144 to regulate the expression of IRS1; interference with its expression can inhibit the proliferation, migration, and invasion of LSCC cells." (PMID 37504269, 2023).
liver disease (5 papers, 2015 to 2023). "Genetic risk factors for liver disease (NAFLD) were associated with lipid and glucose metabolism, including peroxisome proliferator-activated receptor-alpha (PPARA), PPARG, LIPIN1, and insulin receptor substrate 1 (IRS1)." (PMID 33466498, 2021). "Considering the survival-promoting role of IRS-1 in several hepatic diseases, particularly NAFLD, the restoration of this pathway would definitely contribute to the improvement in IR." (PMID 27761469, 2016). "For example, the induction of TNF-α causes phosphorylation of IRS-1 at Ser312 and impedes insulin signaling, especially in HCV patients with more severe liver disorders." (PMID 25645159, 2015). "However, there is also a different voice, such as another research which was conducted to detect the expression of human IRS-1 and insulin signaling proteins under different pathophysiologic conditions of hepatic disease." (PMID 32695243, 2020). "In the IGF1/IRS1/Akt/mTOR pathway, decreased IGF-1 induced by liver disease and decreased ubiquitination of IRS-1 induced by epigenetic alterations block the pathway upstream and downstream respectively, leading to the development of sarcopenia." (PMID 37881635, 2023). "Considering the limited studies and patient population, our research was designed to determine the expression and significance of IRS-1 in human HCC, compared with other liver diseases." (PMID 32695243, 2020).
neuroblastoma (5 papers, 2012 to 2025). Neuroblastoma (NB) is the most common solid, extracranial childhood tumor. "Neuroblastoma cells are known to exclusively express IRS-2 over IRS-1, consistent with these results." (PMID 24349301, 2013). "In the IGF1R pathway, we find increased dependency on IGF2BP1, IGF1R, IRS1, and IRS2 in neuroblastoma, Ewing’s sarcoma, pancreas, myeloma, or rhabdomyosarcoma." (PMID 35382456, 2022). "Specifically, IRS-2, not IRS-1, protects neuroblastoma cells from caspase-mediated apoptosis and promotes tumorigenesis." (PMID 24349301, 2013).
sarcopenia (5 papers, 2017 to 2025). Progressive decline in muscle mass due to aging which results in decreased functional capacity of muscles. "Recently, the IRS1/Akt/FoxO1 signaling pathway was reported to appear in sarcopenia." (PMID 29271915, 2017).
SHORT syndrome (5 papers, 2015 to 2025). A rare disorder characterized by multiple congenital anomalies, including short stature, hyperextensibility of joints, ocular depression, Rieger anomaly and teething delay in which the cause of the disease is a mutation in PIK3R1 gene. "Results of immunoblotting of anti-Irs1 immunoprecipitates from 3T3-L1 cells expressing wild-type, APDS2-associated, or SHORT syndrome-associated mutant p85α under the control of doxycycline (Dox) are shown." (PMID 39835783, 2025). "Attenuated insulin-induced association of p110α with Irs1 in the presence of activating p110 delta syndrome 2 (APDS2) and SHORT syndrome mutant p85α." (PMID 39835783, 2025). "The mutation R649W, the most common p85α variant associated with SHORT syndrome, causes impaired PI3K signaling, probably by defective association with tyrosine-phosphorylated protein effectors, such as IRS-1." (PMID 28143957, 2017).
squamous cell carcinoma (5 papers, 2012 to 2023). A carcinoma arising from squamous epithelial cells. "Meanwhile, low IRS-1 cytoplasmic expression also showed a trend toward association with decreased overall survival in squamous cell carcinoma patients." (PMID 34443299, 2021). "High IRS-2 expression was significantly associated with decreased overall survival in adenocarcinoma (ADC) patients, whereas low IRS-1 cytoplasmic expression showed a trend toward association with decreased overall survival in squamous cell carcinoma (SCC) patients." (PMID 31393907, 2019). "When expression in different histological types was compared, the expressions of ATM, Ku80, IGFBP2, IRS1-pS307, and S6 were significantly higher in neuroendocrinal carcinoma than in adenocarcinoma or squamous cell carcinoma (p<0.05)." (PMID 22348039, 2012). "In this study, we assessed the expression patterns of IRS-1 and IRS-2 in NSCLC to identify associations between IRS-1 and IRS-2 expression levels and survival outcomes in the two major histological subtypes of NSCLC, adenocarcinoma (ADC) and squamous cell carcinoma (SCC)." (PMID 31393907, 2019).
acute myocardial infarction (4 papers, 2013 to 2024). Necrosis of the myocardium, as a result of interruption of the blood supply to the area. "An increased mRNA expression of Irs-1, Prkcz (a downstream of IRS-1 and PI3K), pyruvate dehydrogenase kinase (Pdk)-1, and Pdk-2 was observed in diabetic rats after myocardial infarction." (PMID 26229969, 2015).
dementia (4 papers, 2017 to 2022). Loss of intellectual abilities interfering with an individual's social and occupational functions. "The presence of dementia was significantly associated with JNK and negatively associated with IKKβ and IRS1." (PMID 27106634, 2017). "The analysis in participants with dementia and AD pathology revealed in addition to the significant negative relationship with IKKβ, a significant negative association with IRS1 and a significant positive relationship with JNK." (PMID 27106634, 2017). "Among participants with dementia and AD pathology, significant positive correlations were observed between JNK with PKR and IRS1, and PKR with IRS1." (PMID 27106634, 2017). "Not only the APP gene is responsible for dementia in DS, GATD3A, SOD1, ERG, BACE2, DSCR1/RCAN1, APOE (19q13.32), BACE1 (11q23.3), IL1B (2q14.1), GSAP (7q11.23), UBB (17p11.2), and IRS1 (2q36.3) genes may also play a major role in dementia in DS." (PMID 35676933, 2022). "Thus, participants with dementia and AD pathology are likely to have expression of relatively higher levels of JNK and lower levels of IKKβ and IRS1 relative to participants without dementia." (PMID 27106634, 2017). "Among participants without dementia, the significant relationships observed between metaflammasome proteins and AD neuropathology were negative between: IKKβ and meningeal CAA; IRS1 and diffuse and neuritic plaques; and JNK and neuritic plaques." (PMID 27106634, 2017).
hyperandrogenism (4 papers, 2006 to 2025). Excessive secretion of androgens from the adrenal glands or gonads. "Therefore, we assume that enhanced PI3K-AKT and IRS-1 signalings in the ovary may be one of the reasons for hyperandrogenism and related PCOS-like features in our model." (PMID 33525535, 2021).
leukemia (4 papers, 2010 to 2025). A malignant (clonal) hematologic disorder, involving hematopoietic stem cells and characterized by the presence of primitive or atypical myeloid or lymphoid cells in the bone marrow and the blood. "Four of these genes were reported for leukemias (IRS1, RUNX2, CCDC50 and ROBO3) and four others were reported to be involved in other types of cancers (NSG1, CAMK1D, CD3E, KLF8)." (PMID 41146244, 2025). "Our laboratory and others have demonstrated that significant functional cross-talk between AMPK, mTOR, IGF-1R/IRS-1, and Akt signaling factors occur in leukemia cells." (PMID 20863384, 2010).
lipodystrophy (4 papers, 2018 to 2024). A congenital or acquired disorder characterized by abnormal loss or redistribution of the adipose tissue in the body. "The weighted loci in this cluster (N = 37 loci) are lipodystrophy and adiposity-related variants (PPARG, IRS1, LYPLAL1, and DNAH10)." (PMID 37790568, 2023).
Nephropathy (4 papers, 2019 to 2025). A nonspecific term referring to disease or damage of the kidneys. "Cluster 3 (n = 95) comprised patients with low miR-375 expression and low IRS1 and AKT2 activity, poor glucose control, and the lowest adherence, as well as the most cardiovascular disease and nephropathy." (PMID 40786421, 2025).
psoriasis (4 papers, 2019 to 2025). An autoimmune condition characterized by red, well-delineated plaques with silvery scales that are usually on the extensor surfaces and scalp. "The chronic inflammation inherent in psoriasis leads to the activation of immune cells and the release of cytokines that disrupt insulin signaling pathways, mainly through the serine phosphorylation of insulin receptor substrate-1 (IRS-1), thereby promoting insulin resistance." (PMID 40277935, 2025). "With respect to diabetes, higher rates of psoriasis (~1.76-fold), especially of severe psoriasis (~2.1-fold), have been reported, and elevated levels of TNF seem mainly to be responsible via JNK activation and subsequent IRS-1 phosphorylation." (PMID 32010143, 2019).
Arthritis (3 papers, 2019 to 2022). Inflammation of a joint. "Next, a deep histological analysis of intracellular IGF1R signalling in spleen of arthritis mice was performed by staining IRS1 and FOXO1." (PMID 36105797, 2022).
Cachexia (3 papers, 2011 to 2021). Severe weight loss, wasting of muscle, loss of appetite, and general debility related to a chronic disease. "A SNP in IRS1 (rs2234931) was significantly associated with cachexia in the exploratory analysis." (PMID 21934689, 2011).
hypertriglyceridemia (3 papers, 2019 to 2024). A laboratory test result indicating elevated triglyceride concentration in the blood. "IL-6 and IL-1 β are involved in IR, which is mediated through the underexpression of insulin receptor substrate-1 (IRS-1), and also suppress the activity of lipoprotein lipase, resulting in hypertriglyceridemia." (PMID 39063997, 2024).
insulinoma (3 papers, 2014 to 2022). "Some studies showed that palmitate increased serine phosphorylation of IRS-1 and apoptosis in rat insulinoma cells and decreased Akt phosphorylation and glucose uptake." (PMID 36619574, 2022). "In rat insulinoma cells, metformin attenuated ER stress, IRS-1 phosphorylation, and apoptosis." (PMID 36619574, 2022).
ischemic stroke (3 papers, 2012 to 2018). A stroke disorder caused by obstruction of blood flow to the brain, due to thrombotic (local blood clot formation) or embolic (due to a blood clot or other material traveling from another site) event. "Conclusively, the IRS-1 gene polymorphism Gly972Arg should be considered as an important factor in the prevention and treatment of ischemic stroke." (PMID 30305144, 2018). "This study shows that IRS-1 gene polymorphism Gly972Arg acts as the risk factor for ischemic stroke." (PMID 30305144, 2018). "This study aims to identify insulin receptor substrate 1 (IRS-1) gene polymorphism Gly972Arg as the risk factor for ischemic stroke among Indonesian subjects." (PMID 30305144, 2018). "Pathogenesis and molecular changes occurring in IRS-1 gene polymorphism Gly972Arg acting as the factor for ischemic stroke take place because of a mutation of the amino acid glycine by arginine at codon 972 substitution (G972R)." (PMID 30305144, 2018). "The distribution of nucleotide IRS-1 gene polymorphism Gly972Arg in the ischemic stroke vs health controls for GG were 32.2% vs 41.5%, for GR were 16% vs 7.6%, and for RR were 0.5% vs 1.9%." (PMID 30305144, 2018). "IRS-1 gene polymorphism Gly972Arg was found as significant risk factor for ischemic stroke [odds ratio of 2.6 (1.27–5.27); CI 95%, p = 0.008]." (PMID 30305144, 2018). "Next, we statistically analyzed the role of IRS-1 gene polymorphism Gly972Arg as the factor risk for ischemic stroke." (PMID 30305144, 2018). "It has been reported that IRS-1 polymorphism genotype Gln192Arg is associated with the increased incidence of ischemic stroke." (PMID 30305144, 2018). "Although IRS-1 gene polymorphism Gly972Arg might serve as a predictor for ischemic stroke in the future, it is difficult to be considered as actionable target." (PMID 30305144, 2018). "The current study addresses the question on whether IRS-1 gene polymorphism Gly972Arg acts as the risk factor for ischemic stroke among Indonesian subjects." (PMID 30305144, 2018). "We found that IRS-1 gene polymorphism Gly972Arg was a significant risk factor for ischemic stroke." (PMID 30305144, 2018).
leiomyoma (3 papers, 2013 to 2021). A well-circumscribed benign smooth muscle neoplasm characterized by the presence of spindle cells with cigar-shaped nuclei, interlacing fascicles, and a whorled pattern. "The genes associated with “cancer process” contained potentially novel or relevant candidate genes for leiomyoma formation such as IRS1, COL4A1, COL4A2, COL6A3, and GSTM5." (PMID 23818951, 2013). "From these findings, we speculate that tumor stem cells with overexpression of IRS1 respond to estrogen by acquiring ER alpha expression and stimulating ER alpha activities, resulting in the development of leiomyomas." (PMID 23818951, 2013). "In addition, mRNA levels of IRS1 in leiomyomas were higher than those in myometrium in all the 10 samples." (PMID 23818951, 2013). "First, we examined the DNA methylation status of the IRS1 and COL4A1 using combined bisulfite restriction analysis in Case1, Case2, Case3 and additional 7 paired samples of leiomyoma and matched myometrium." (PMID 23818951, 2013). "Aberrant DNA methylation and its related transcriptional aberration in cancer-related genes such as IRS1 may represent a critical initial mechanism that triggers transformation of a single tissue stem cell to a tumor stem cell, which will eventually develop into a monoclonal leiomyoma tumor." (PMID 23818951, 2013). "IRS1 is also reported to be involved in the upregulation of collagen genes, including COL4A1, COL4A2 and COL6A3, suggesting that IRS1 possibly contributes to the leiomyoma nodule formation by upregulating the gene expression of COL4A1, COL4A2, and COL6A3." (PMID 23818951, 2013).
liver fibrosis (3 papers, 2022 to 2024). "Consistent with the results of previous animal studies, the investigation of the cell insulin signaling pathway suggested that the H-L + HFD-induced liver fibrosis was mediated by gut microbiota through disruption of the gut barrier TLR4/MYD88 and liver IRS1/Akt/mTOR signaling pathways." (PMID 36204709, 2022).
liver inflammation (3 papers, 2012 to 2021). "HCV-induced liver inflammation and cirrhosis may reduce the uptake of glucose by hepatic cells, then affect the glucose metabolism; HCV infection may also impair IRS-1 tyrosine phosphorylation." (PMID 31195990, 2019).
malignant mesothelioma (3 papers, 2017 to 2021). A malignant neoplasm of the pleura or peritoneum, arising from mesothelial cells. "miR-126 acts as a tumor suppressor downregulating IRS1 (Insulin Receptor Substrate 1) and restoring the mitochondrial TCA metabolism in malignant mesothelioma H28 and Met5A cell lines." (PMID 31952362, 2020).
memory impairment (3 papers, 2019 to 2022). "PKR activation occurs in a TNFα-dependent manner and this, in turn, results in IRS1 inhibition, synaptic loss and memory impairment." (PMID 34986876, 2022). "In STZ mice that had already developed memory impairment, the phosphorylation levels of hippocampal IRS1 at Ser residues in STZ mice were comparable to those in WT mice." (PMID 31426549, 2019). "Our findings indicate that the phosphorylation of IRS1 at disease-specific Ser residues in the hippocampus may be a potential marker of Aβ-unrelated memory impairments induced by T2DM and aging." (PMID 31426549, 2019). "Therefore, we investigated the phosphorylation levels of hippocampal IRS1 at Ser sites and the activities of downstream factors involved in memory impairment in 35-week-old (middle-aged) DIO mice fed a 60% HFD for 32 weeks." (PMID 31426549, 2019). "In middle-aged DIO and aged mice, Aβ-unrelated memory deficits are accompanied by increased basal phosphorylation of hippocampal IRS1 at specific Ser residues, whereas Aβ-unrelated memory impairments develop in STZ mice without the modification of IRS1." (PMID 31426549, 2019).
multiple myeloma (3 papers, 2018 to 2022). "In human multiple myeloma cell lines, IGF1 induced proliferation and antiapoptotic effects via IRS1-dependent PI3K/AKT and MAPK activation, even in IL6-independent cell lines, indicating that the IGF1R/IRS1 axis plays an important role in the development and progression of this disease." (PMID 30328953, 2018).
neuropathy (3 papers, 2020 to 2025). A disorder affecting the nervous system that manifests with pain, tingling, numbness, and/or muscle weakness. "This analysis was aimed at identifying whether IRS1 modulation could contribute to differential vulnerability or resilience to neuropathy between males and females." (PMID 41158618, 2025).
Parkinson disease (3 papers, 2020 to 2023). A progressive degenerative disorder of the central nervous system characterized by loss of dopamine producing neurons in the substantia nigra and the presence of Lewy bodies in the substantia nigra and locus coeruleus. "The dopamine-mediated JAK/STAT pathway gene network reported to be evoked in Parkinson disease also proved to be elevated specifically in the A20 group (Jak22, Irs1 DEGs)." (PMID 35052361, 2021).